CDC27 (cell division cycle 27)
Description:
Component of the anaphase promoting complex/cyclosome (APC/C), a cell cycle-regulated E3 ubiquitin ligase that controls progression through the cell cycle. APC/C acts by mediating ubiquitination and subsequent degradation of target proteins: it mainly mediates the formation of 'Lys-11'-linked polyubiquitin chains and, to a lower extent, the formation of 'Lys-48'- and 'Lys-63'-linked polyubiquitin chains. APC/C catalyzes assembly of branched 'Lys-11'-/'Lys-48'-linked branched ubiquitin chains on target proteins. APC/C is activated by CDC20 in the metaphase/anaphase transition of cell cycle, targeting the degradation of cyclin B and securin. APC/C is regulated by the mitotic checkpoint complex (MCC), which inhibits APC/C and delays chromosome segregation.
Synonyms: APC3; CDC27Hs; ANAPC3; D0S1430E; D17S978E; NUC2; H-NUC; HNUC
Tractability: PROTAC: ubiquitination databases record sites on it; its protein half-life has been measured.
Gene: Protein-coding gene on chromosome 17 (47,117,703 to 47,189,422, reverse strand). Ensembl gene ENSG00000004897.
Subcellular location: Nucleus; Cytoplasm, cytoskeleton, spindle
Subcellular location (Human Protein Atlas): Nucleoplasm
Pathways (Reactome):
Cell Cycle: APC-Cdc20 mediated degradation of Nek2A; APC/C:Cdc20 mediated degradation of Cyclin B; APC/C:Cdc20 mediated degradation of Securin; APC/C:Cdc20 mediated degradation of mitotic proteins; APC/C:Cdh1 mediated degradation of Cdc20 and other APC/C:Cdh1 targeted proteins in late mitosis/early G1; Autodegradation of Cdh1 by Cdh1:APC/C; Cdc20:Phospho-APC/C mediated degradation of Cyclin A; Conversion from APC/C:Cdc20 to APC/C:Cdh1 in late anaphase; Inactivation of APC/C via direct inhibition of the APC/C complex; Phosphorylation of the APC/C; Regulation of APC/C activators between G1/S and early anaphase; Separation of Sister Chromatids
DNA Replication: Assembly of the pre-replicative complex; CDK-mediated phosphorylation and removal of Cdc6
Cellular responses to stimuli: Senescence-Associated Secretory Phenotype (SASP)
Disease: Aberrant regulation of mitotic exit in cancer due to RB1 defects
Gene expression (Transcription): Transcriptional Regulation by VENTX
Immune System: Antigen processing: Ubiquitination & Proteasome degradation
Gene Ontology:
Molecular function: protein binding; protein phosphatase binding; enzyme-substrate adaptor activity
Biological process: anaphase-promoting complex-dependent catabolic process; metaphase/anaphase transition of mitotic cell cycle; protein branched polyubiquitination; protein K11-linked ubiquitination; protein K48-linked ubiquitination; cell division; protein ubiquitination; regulation of meiotic cell cycle; regulation of mitotic cell cycle
Cellular component: anaphase-promoting complex; centrosome; cytoplasm; mitotic spindle; nucleoplasm; nucleus; spindle; cytosol
Genetic constraint (gnomAD): Loss-of-function variants: 0 observed, 7.88 expected, observed/expected ratio (o/e) 0, 90% interval 0 to 0.38. That is too few expected variants to judge how well the gene tolerates losing a copy. Missense variants: 75 observed, 117.05 expected, observed/expected ratio (o/e) 0.64, 90% interval 0.53 to 0.78. Synonymous variants: 37 observed, 37.79 expected, observed/expected ratio (o/e) 0.98, 90% interval 0.75 to 1.29.
Homologues: Orthologues: macaque CDC27 (99% identical), dog CDC27 (99% identical), rabbit CDC27 (99% identical), guinea pig CDC27 (99% identical), rat Cdc27 (98% identical), mouse Cdc27 (97% identical), pig CDC27 (95% identical), tropical clawed frog cdc27 (89% identical), zebrafish cdc27 (81% identical), Drosophila melanogaster Cdc27 (44% identical), Caenorhabditis elegans mat-1 (29% identical). Paralogues in human: CDC23 (15% identical), CDC16 (15% identical), ANAPC7 (12% identical).
Diseases named in the same sentence as CDC27 in open-access papers:
CDC27 is named in the same sentence as 71 diseases in open-access papers, as found by Europe PMC text mining. Sharing a sentence is not in itself a finding about the gene and the disease. The quoted sentences say what the papers report.
breast cancer (13 papers, 2014 to 2024). A primary or metastatic malignant neoplasm involving the breast. "In breast cancer, homozygous or heterozygous rs11570443 (CT or CC) along with homozygous rs12601027 (TT) in CDC27 have an association with the risk of cancer." (PMID 33750395, 2021). "In another study which was about the role of 1084 functional germline variants in breast cancer, rs764792 in CDC27 was correlated with the risk of high-grade breast cancer." (PMID 33750395, 2021). "For example, the expression of APC3/CDC27 was significantly elevated in gastric cancer but downregulated in several breast cancer cell lines." (PMID 36499653, 2022). "CDC27 is a core element of the anaphase-promoting complex (APC) and is associated with controlling mitotic checkpoints to ensure chromosomal integrity, and APC or CDC27 was downregulated in breast cancer." (PMID 33916931, 2021). "In breast cancer patients, immunohistochemial evaluations of CDC27 along with securin are the valuable prognostic biomarkers after lymph node examination." (PMID 33750395, 2021). "In the case of breast cancer, the CDC27 has been demonstrated to be a promising biomarker in predicting the disease progression and prognostication." (PMID 25496518, 2014). "CDC27 at mRNA level has heterogeneous behavior in some malignancies such as breast cancer." (PMID 33750395, 2021). "Supporting the roles of ERLIN2 in stabilizing Cyclin B1 protein and enhancing Cyclin B1/Cdk1 function in breast cancer cells, levels of Cyclin B1 and phosphorylated Cdc27 were increased in ERLIN2-expressing MCF10A cells but decreased in ERLIN2-knockdown SUM225 cells, compared with their controls." (PMID 27462423, 2015). "Among them, 18 genes were essential for cancer cell proliferation, such as NSF for breast cancer, CCND1 for renal cell cancer, DHX16 for lung cancer, CDC27 for ovarian cancer, and CTDP1 for prostate cancer." (PMID 39025880, 2024). "A number of the identified CD47-dependent genes including MBP1, TBL1XR1, girdin, cyclin D1, CDC27, SPAG9, and JAK1 have reported functions in breast cancer progression." (PMID 26840086, 2016). "CDC27 protein level in Non-hodgkin's lymphomas, prostate, glioma, breast cancer and renal cell carcinomas was very low or absent in some samples." (PMID 33750395, 2021). "Indeed, knockdown of APC core subunits Cdc27 and APC10 failed to escalate p-Y419-Src in breast cancer cells." (PMID 31420536, 2019).
colorectal cancer (8 papers, 2016 to 2022). A primary or metastatic malignant neoplasm that affects the colon or rectum. "In our study, we explored the biological and clinical significance of CDC27 in colorectal cancer (CRC) growth and progression and investigated the underlying molecular mechanisms." (PMID 26821069, 2016). "CDC27 plays a key role in colorectal cancer as CDC27 expression is significantly correlated with tumor progression and poor patient survival." (PMID 33367978, 2021). "The possibility of relation between CDC27 expression in CSCs and stemness features in colorectal cancer has been evaluated." (PMID 33750395, 2021). "Studies have shown that overexpression of CDC27 promotes the proliferation of colorectal cancer and the cell-dependent approach promotes the ability to transfer and form balls." (PMID 33329727, 2020). "CDC27 promotes the progression and affects PD-L1 expression in T-cell lymphoblastic lymphoma, and also promotes epithelial-to-mesenchymal transition in colorectal cancer." (PMID 33414811, 2020). "A study has reported that cell division cycle 27 (CDC27), a core subunit of the anaphase-promoting complex/cyclosome, downregulates p21 mRNA levels to promote proliferation of colorectal cancer cells." (PMID 31575057, 2019). "CDC27 overexpression is in harmony with the tumor size, TNM (tumor (T), nodes (N), and metastases (M)) stage and distant metastasis in colorectal cancer (CRC)." (PMID 33750395, 2021). "CDC27 by modulating ID1 can downregulate the expression of epithelial markers (ZO-1 and Ecadherin), and adversely upregulate mesenchymal markers (ZEB1 and Snail) to promote metastasis in colorectal cancer cell lines (HCT116 and DLD1)." (PMID 33750395, 2021).
colon carcinoma (5 papers, 2011 to 2016). "Considering also the highest expression in adjacent tissues, three more genes show an agreement between expression and pathology location (the endometrial cancer genes MORC4 and TXNDC8 most highly expressed in the myometrium and colon cancer gene CDC27 most highly expressed in the ileum)." (PMID 26856619, 2016).
gastric cancer (5 papers, 2020 to 2022). A primary or metastatic malignant neoplasm involving the stomach. "In a recent study in gastric cancer, it was shown that CDC27 somatic mutations may be independently associated with peritoneal metastasis." (PMID 33750395, 2021). "In addition, overexpression of CDC27 induces invasion and migration by gastric cancer cells, which is associated with downregulation of the EMT-related biomarker E-cadherin and upregulation of vimentin." (PMID 32710728, 2020). "Enhanced expression of CDC27 protein was in agreement with the relative expression of EMT biomarkers in gastric cancer tissues and was correlated with clinicopathological properties such as TNM stage and lymph node metastasis." (PMID 33750395, 2021). "The vast majority of cancers indicated moderate to strong expression of CDC27 protein including colorectal, testis, thyroid, gastric cancers and lung adenocarcinoma." (PMID 33750395, 2021). "Furthermore, in gastric cancer tissues, enhanced expression of CDC27 protein was in harmony with the relative expression of EMT biomarkers (E-cadherin, Vimentin and Twist)." (PMID 33750395, 2021).
pulmonary fibrosis (4 papers, 2020 to 2025). Chronic progressive interstitial lung disorder characterized by the replacement of the lung tissue by connective tissue, leading to progressive dyspnea, respiratory failure, or right heart failure. "It has been demonstrated to upregulate the expression of CDC27 in a BLM-induced pulmonary fibrosis mouse model." (PMID 38462601, 2024). "Lnc-TUG1 promotes pulmonary fibrosis progression via up-regulating CDC27 and activating PI3K/Akt/mTOR pathway." (PMID 39133718, 2024). "Collectively then, these findings indicate that downregulation of hsa_circ_0044226 attenuates pulmonary fibrosis in vitro and in vivo by inhibiting CDC27, which in turn suppresses EMT." (PMID 32710728, 2020). "A study on idiopathic pulmonary fibrosis showed that hsa_circ_0044226 promotes EMT by upregulating CDC27, and its knockdown could inhibit CDC27, thus inhibiting the progression of pulmonary fibrosis." (PMID 41458288, 2025). "Furthermore, hsa_circ_0044226 knockdown decreased the expression of CDC27 in BLM-induced pulmonary fibrosis mouse model." (PMID 32710728, 2020). "In addition, downregulation of hsa_circ_0044226 could attenuate pulmonary fibrosis in vitro and in vivo by inhibiting CDC27." (PMID 32710728, 2020). "Notably, CDC27 protein contributes to EMT in human cancers, and EMT also likely contributes to lung fibrosis." (PMID 32710728, 2020).
glioma (3 papers, 2017 to 2021). A benign or malignant brain and spinal cord tumor that arises from glial cells (astrocytes, oligodendrocytes, ependymal cells). "Here we report that mir-218-2 is highly expressed in glioma cell lines and promotes glioma growth, invasion, and migration, as well as drug susceptibility through its targeting of Cell Division Cycle 27 (CDC27)." (PMID 27974673, 2017). "Downregulation of CDC27 in glioma, as a core component of APC/C, leads to inadequate ubiquitination of securin and various cyclins such as cyclinA1/2, cyclinB1, and cyclinD1 and their elevated expression at protein level." (PMID 33750395, 2021). "Increased chemoresistancy of glioma cells to beta-lapachone (β-lap, as an antineoplastic agent) has been attributed to CDC27 downregulation." (PMID 33750395, 2021). "Our results indicate that the overexpression of CDC27 counteracted the function of mir-218-2 in glioma cells." (PMID 27974673, 2017). "Together, these data implicate CDC27 as a functionally relevant target of mir-218-2 in glioma cells." (PMID 27974673, 2017). "Restoration of CDC27 by transfecting the plasmid into mir-218-2 cells reversed the effects of mir-218-2 in glioma cells compared to the vector." (PMID 27974673, 2017). "To further investigate this, we evaluated CDC27 protein levels in glioma cell lines compared to normal human glia cells." (PMID 27974673, 2017). "These in vivo observations suggest that mir-218-2 depletion decreases glioma carcinogenesis by regulating CDC27 expression." (PMID 27974673, 2017). "Taken together, these data suggest that mir-218-2 modulates the APC/Cubiquitin–proteasome pathway by targeting CDC27 in glioma cells." (PMID 27974673, 2017). "Up-regulation of mir-218-2 significantly decreased CDC27 levels in glioma cells, whereas down-regulation of this miRNA or restoring CDC27 expression induced the opposite effect." (PMID 27974673, 2017). "Taken together, our findings suggest that mir-218-2 promotes glioma progression through the CDC27/APC ubiquitin–proteasome pathway, and promotes the invasion, migration, and actin organization through the modulation of cell junction and focal adhesion proteins." (PMID 27974673, 2017). "Our results indicated a decline in CDC27 protein levels in glioma cells." (PMID 27974673, 2017). "Meanwhile, CDC27 enhanced the chemosensitivity of glioma cells to β-lap." (PMID 27974673, 2017). "CDC27 downregulation may play a crucial role in carcinogesis and drug resistance in glioma." (PMID 33750395, 2021). "Cell division cycle 27 (CDC27), the downstream target of mir-218-2, is involved in the regulation of glioma cells." (PMID 27974673, 2017).
lung adenocarcinoma (3 papers, 2013 to 2021). A carcinoma that arises from the lung and is characterized by the presence of malignant glandular epithelial cells. "We identified several targetable pathways in EGFR/KRAS/ALK-negative lung adenocarcinoma including PI3K/mTOR signaling (TSC1, PIK3CA, AKT2), receptor tyrosine kinase signaling (ERBB4), cell cycle regulation (CHEK2, CDC27), and DNA repair (PARP4)." (PMID 24576404, 2014).
lung carcinoma (3 papers, 2013 to 2024). "In summary, SMC6, CDC27, CDC7, RACGAP1, SMC4, NCF1,2,4, SELPLG and CFP are significantly associated with T2DM and lung cancer, making them potential target genes for disease prediction and treatment in the future." (PMID 38468345, 2024). "PTK2, PGF, SLCO4A1 and Cdc27 are among the genes in Merged-module whose over-expression has been reported in different cancers including lung cancer and we have shown it as well." (PMID 23874428, 2013). "CDC27 has not been investigated in diabetes thus far, and we need to verify further its potential as a common target in lung cancer and diabetes." (PMID 38468345, 2024).
lupus (2 papers, 2022 to 2025). "The CDC27 gene, as found through WES combined with multiple analytical method may be a causative gene of lupus." (PMID 35418986, 2022). "The mechanism of abnormal CDC27 expression in lupus still needs to be further explored." (PMID 35418986, 2022). "In addition, the expression level of CDC27 correlated with the activity of lupus and had certain value in predicting the condition." (PMID 35418986, 2022). "In the present study, peripheral blood of familial SLE patients and healthy controls was submitted to qPCR to detect CDC27, and the results showed low CDC27 expression in lupus patients." (PMID 35418986, 2022). "QPCR was performed to detect for CDC27 in the PBMCs of the SLE familial patients, sporadic lupus patients, and healthy people." (PMID 35418986, 2022). "We speculate that the downregulation of CDC27 in lupus may lead to immune disorders." (PMID 35418986, 2022). "The CDC27 expression was upregulated in PBMCs from SLE patients with reduced lupus activity after immunotherapy (P<0.05)." (PMID 35418986, 2022). "QPCR was performed to detect for CDC27 in the PBMCs of the SLE family patients, sporadic lupus patients, and healthy people." (PMID 35418986, 2022). "A study on CDC27 in systemic lupus erythematosus (SLE) showed that it was positively correlated with SLE disease activity and that inhibition of CDC27 could slow down disease progression." (PMID 41458288, 2025). "Quantitative polymerase chain reaction (qPCR) showed that compared with healthy individuals, the expression trend of CDC27 in patients with sporadic lupus was the same as that in familial patients, indicating that CDC27 might serve as a marker for the diagnosis of SLE." (PMID 35418986, 2022). "To date, there had been no direct study on the relationship between CDC27 and lupus." (PMID 35418986, 2022). "CDC27 may serve as a marker for the diagnosis of SLE and is closely related to the lupus activity." (PMID 35418986, 2022).
nasopharyngeal carcinoma (2 papers, 2021 to 2025). A carcinoma arising from the nasopharyngeal epithelium. "Recent research has indicated that ITCH mediates SIX1 ubiquitination and influences the development of nasopharyngeal carcinoma via the CDC27-cyclin B1 signaling pathway." (PMID 40170095, 2025). "Irradiated CNE-1 cells (nasopharyngeal carcinoma cells) showed decreased level of CDC27, which suggested CDC27 is a part of mechanism of radiosensitivity." (PMID 33750395, 2021).
neuroblastoma (2 papers, 2016 to 2022). Neuroblastoma (NB) is the most common solid, extracranial childhood tumor. "Similar to ferrostatin, downregulation of CDC27 also impeded the inhibitory effect of RSL3 on cell growth in SK-N-SH cells, while upregulation of CDC27 made SH-SY5Y cells more sensitive to RSL3-induced ferroptosis, hinting that CDC27 accelerated RSL3-induced ferroptosis in neuroblastoma cells." (PMID 35242701, 2022). "In addition, similar results were obtained from wound healing assays, in which CDC27 accelerated the wound healing abilities of both SK-N-SH and SH-SY5Y cells, which reinforced the conclusion that CDC27 promoted metastasis in neuroblastoma." (PMID 35242701, 2022). "Collectively, our data is the first to report that the CDC27/ODC1 axis promotes tumorigenesis and acts as a positive regulator of ferroptosis in NB, highlighting that CDC27 may represent a novel therapeutic strategy and prognostic biomarker in neuroblastoma." (PMID 35242701, 2022).
ovarian carcinoma (2 papers, 2021 to 2024). A malignant neoplasm originating from the surface ovarian epithelium. "Therefore, CDC27 as an oncogene, is one of the related genes proposed for growth inhibiting action of Eribulin and Paclitaxel on ovarian cancer cells." (PMID 33750395, 2021). "Finally, after treatment of ovarian cancer cells with Eribulin and Paclitaxel (two anti-cancer drugs), expression of CDC27 was decreased at both mRNA and protein level." (PMID 33750395, 2021).
pancreatic cancer (2 papers, 2017 to 2020). "Using multivariate Cox regression analysis, we detected eight optimal ubiquitination-related genes (RNF7, NPEPPS, NCCRP1, BRCA1, TRIM37, RNF25, CDC27, and UBE2H) and then used them to construct a risk model to predict the prognosis of pancreatic cancer patients." (PMID 33414811, 2020).
prostate carcinoma (2 papers, 2019 to 2024). A carcinoma that arises from epithelial cells of the prostate gland. "CDC27 is a tumor suppressor, its downregulation inhibits the proliferation of cancer cells, POLR3G is required for proliferation, its depletion triggers proliferative arrest and differentiation of prostate cancer cells." (PMID 31540229, 2019).